AFP (alpha fetoprotein)
Diseases named in the same sentence as AFP in open-access papers (continued):
Sharing a sentence is not in itself a finding about the gene and the disease.
lymph node metastasis (continued). "Compared with ordinary-type of GC, AFP-positive GC is more aggressive, and more prone to early lymph node metastasis and distant metastasis." (PMID 35847953, 2022). "Univariate analysis showed that ALT ≤ 30 IU/L, AFP ≤ 400 ng/mL, extrahepatic metastasis, lymph node metastasis, and ECW/TBW ≤ 0.400 were significant factors contributing to extension of PPS." (PMID 35041693, 2022). "During curative treatment significantly rising AFP levels led to the assumption of chemo-resistant disease, mandating the initiation of salvage chemotherapy and surgical removal of the putative lymph node metastases." (PMID 31906360, 2020). "Our study revealed that high E2F2 expression was closely related to the worse histologic grade, advanced clinical stage, more lymph node metastasis, and higher serum AFP value." (PMID 33115417, 2020). "But AFP level ≥400 ng/ml, tumor number ≥2, tumor size ≥5 cm, lymph node metastasis, distant metastasis, major and microvascular invasion and positive margin increased the HR by different fold respectively, according to multivariate analysis." (PMID 31567946, 2019). "The results indicated AST, GGT, WBC, NLR, PTA, AFP ≥ 400 ng/mL, tumor number ≥ 3, tumor diameter ≥ 5 cm, lymph node metastasis, and portal vein involvement to be independent prognostic variables." (PMID 28143427, 2017). "Distinctive features of patients with hepatitis B virus-associated ICC included younger age, preponderance of male patients, frequent elevation of alpha-fetoprotein, and infrequent lymph node metastasis." (PMID 28030846, 2017). "Elevated AFP is rarely reported in CUP cases presenting with isolated lymph node metastasis." (PMID 41561743, 2025). "In summary, this study reveals that larger tumor size, poor tumor histological differentiation, and regional lymph node metastasis were associated with a higher risk of extrahepatic metastasis, but not AFP." (PMID 36127436, 2022). "Based on multivariable analysis, the prognostic factors for OS were older age (HR 1.736, 95% CI [1.396–2.157], p < 0.001), lymph node metastasis (HR 1.406, 95% CI [1.093–1.808], p = 0.008), surgical intervention, lower AFP level (HR 0.757, 95% CI [0.587–0.976], p = 0.032) and histologic type." (PMID 32110489, 2020). "Furthermore, the protein level of PHF2 was also correlated with lymph node metastasis-pN status, depth of invasion and serum AFP (P < 0.05, paired χ2 test)." (PMID 31214616, 2019). "In addition, a panel with BRCA1 mutation, BRCA2 mutation, and five serum markers (AFP, CA125, CA19‐9, CA242 and HE4) showed a good performance for identifying patients with lymph node metastasis (AUC = 0.843, Sensitivity = 0.600, Specificity = 0.902)." (PMID 30972954, 2019). "Previous studies in HCC patients reported tumor-related factors including microvascular invasion, multiple tumors, lymph node metastasis, and elevation of preoperative serum AFP level were contributing factors of early tumor recurrence, which is consistent with the finding of the present study." (PMID 30606203, 2019). "Besides, neutrophil count significantly correlated with tumor length (p = 0.000), portal vein thrombosis (p = 0.036), lymph node metastasis (p = 0.032), TNM7th stage (p = 0.000) and AFP (p = 0.002)." (PMID 28412745, 2017). "For OS, the significant inferior prognostic factors included the male sex, history of alcohol consumption, ALT, AST, TBil, ALB, ALP, GGT, WBC, NC, LC, NLR, Cr, PTA, AFP ≥ 400 ng/mL, tumor number ≥ 3, tumor diameter ≥ 5 cm, lymph node metastasis, and portal vein involvement (p < 0.05)." (PMID 28143427, 2017). "The data obtained from the univariate analysis revealed that high FAM83D expression, AFP ≥100 ng/ml, a median size tumor ≥5 cm, multiple tumors, TMN stage III–IV, PVTT, distant metastasis or lymph node metastasis, AST ≥40 U/l and NLR ≥2.31 were all associated with a shorter DFS and OS." (PMID 26125229, 2015).
lymph node metastasis (continued). "A comparison of the clinicopathological data between patients with or without lymph node metastasis revealed that the group of patients with lymph node metastasis had a significantly higher total bilirubin (P = 0.009), and a significantly lower alpha fetoprotein (AFP) level (P = 0.035)." (PMID 24760012, 2014). "Compared with Control, both PDOX and DOX could similarly and significantly reduce liver tumor weight and tumor volume by over 40%, ePCI values, retroperitoneal lymph node metastases and lung metastases and serum AFP levels (P < 0.05)." (PMID 23961994, 2013). "Furthermore, anemia and elevated levels of serum CEA, CA19–9 were frequently detected among 80% (28/35), 60% (21/35), 42.9% (15/35) of AFP-producing GC patients, particularly for those with serosal involvement, lymphatic and venous invasion, and lymph node metastasis." (PMID 29254216, 2017). "In addition to a high FAM83D expression level, a value of AFP ≥100 ng/ml, a tumor ≥5 cm, the presence of multiple tumors, TNM stage III-IV, the presence of PVTT, the presence of distant metastasis or lymph node metastasis, AST ≥40 U/l and NLR ≥2.31 were associated with a shorter DFS and OS." (PMID 26125229, 2015). "Moreover, despite the relatively low numbers of patients with complete data, STAT3 overexpression was significantly associated with the depth of invasion and lymph node metastasis (p<0.05) in the AFP-positive and -negative groups." (PMID 23382965, 2013). "The platelet count, serum AFP, CEA, tumor location, tumor differentiation, lymph node metastasis, chemotherapy, and TNM stage were all shown to be significant independent risk factors for CCA patients in a multivariate analysis." (PMID 37308861, 2023). "After correlation analysis, we determined that LINC00221 expression was highly correlated to lymph node metastasis (LNM), clinical grade, TNM staging, and AFP content." (PMID 33836753, 2021). "The patients with higher PRG had higher levels of NLR, PLR, AFP, CEA and CA19-9, and had more possibility of VI, and lymph node metastasis (all p < 0.05)." (PMID 33676467, 2021). "Intermediate prognosis was defined as any of the following: lymph node metastases 5-10 cm in diameter, lung metastases more than four in number or > 3 cm, HCG 5000-50,000 IU l(-1), AFP > 1000 IU l(-1)." (PMID 9743309, 1998). "Clinical data analysis showed that high expression of circGPC3 was significantly correlated with TNM stage and lymph node metastasis but not sex, age or AFP level." (PMID 38561366, 2024). "Compared with AFP-negative GC, AFP-positive GC had higher rates of liver metastasis, lymph node metastasis, venous invasion, and nerve invasion (all P < 0.05)." (PMID 35847953, 2022). "The incidence of lymph node metastasis and venous invasion was higher than AFP-negative GC, which was similar to previous research results." (PMID 35847953, 2022). "In univariate analyses of AFP non-producing gastric adenocarcinoma group, lymph node metastasis, higher TNM stage and increased expression of Bcl-2 were found to be correlated with poor RFS and OS." (PMID 27057629, 2016). "AKR1B10 mRNA level correlated with serum AFP level, TNM stage, and lymph node metastasis." (PMID 26948042, 2016). "Its elevated expression is positively correlated with serum alpha-fetoprotein (AFP) levels, lymph node metastasis, and TNM staging, while exhibiting a negative correlation with the overall survival rate of patients." (PMID 41282486, 2025). "In CCA patients, the extent of CD8 T cell infiltration in tumor tissues exhibits a negative correlation with serum alpha fetoprotein (AFP)levels, tumor size, and lymph node metastasis." (PMID 40070825, 2025). "circSLCO1B7 expression was correlated with the TNM stage, lymph node metastasis and tumor size of HCC patients, but not with patient age, sex or serum AFP." (PMID 38015711, 2023).
lymph node metastasis (continued). "In the multivariate analysis, an AFP level of ≥400 ng/mL was an independent negative prognostic factor for PFS, whereas child B, lymph node metastasis, and treatment method were independent prognostic factors for OS." (PMID 36211350, 2022).
ovarian cancer (74 papers, 1976 to 2025). A primary or metastatic malignant neoplasm involving the ovary. "In many patients with ovarian cancer, elevated AFP is associated with an increase in CA-125, a widely used tumor marker for ovarian cancer, and appears to be more sensitive than CA-125 for tumor tracking, suggesting that further investigation is needed to explore this possibility." (PMID 40430002, 2025). "Useful tumor markers that raise concern for ovarian cancer in children and adolescents include alpha-fetoprotein, lactate dehydrogenase, beta subunit of human chorionic gonadotropin, cancer antigen 125 and inhibin." (PMID 37508611, 2023). "Another study evaluated multiple tumor markers, including AFP, and found that they effectively distinguished ovarian cancer from benign cases and healthy individuals." (PMID 37629546, 2023). "This is the case of the α2,3-SA PSA glycoforms for prostate cancer, core fucosylated-AFP glycoforms (AFP-L3) for hepatocellular carcinoma or CA125-STn for ovarian cancer." (PMID 36009489, 2022). "In the gynecological tract, AFP-producing carcinomas of the ovary and uterine cervix have been described to exhibit this morphology." (PMID 34977100, 2021). "In humans, the combination of HE4 and CA125 expression is currently used in the clinic for accurate diagnosis of malignant ovarian tumours, and AFP is used in the clinic as a tumour marker." (PMID 30739231, 2019). "Epithelial ovarian cancers had been rarely reported to secrete AFP, and AFP-producing EOCs are also extremely rare." (PMID 29933751, 2018). "Primary hepatoid carcinoma of the ovary (HCO) is a very rare type of high-grade invasive malignant ovarian tumor with hepatic differentiation and production of α-fetoprotein (AFP)." (PMID 26213594, 2015). "A high level AFP level in a pre-pubic girl with an adnexal mass is indicative of a malignant ovarian tumor." (PMID 23826706, 2013). "A high AFP level in a pre-pubic girl with an adnexal mass is indicative of a malignant ovarian tumor." (PMID 23826706, 2013). "Therefore, to gain a clearer understanding of the management of AFP-producing EOC and develop effective treatment strategies, it is essential to continuously monitor AFP levels and conduct in-depth research on the function of AFP in ovarian cancer." (PMID 40430002, 2025). "Ovarian cancer that produces AFP is uncommon but usually has a much worse prognosis." (PMID 36114551, 2022). "Except CA125, some serum indicators such as β-hCG, Alpha-fetoprotein (AFP), Anti-Müllerian hormone (AMH), and LDH may also be associated with the prognosis of ovarian cancer." (PMID 36114551, 2022). "In contrast, the most common form of ovarian cancer, epithelial ovarian cancer (EOC), rarely produces AFP compared to ovarian germ cell tumors." (PMID 40430002, 2025). "Routinely determining blood biomarkers, such as CA125, carcinoembryonic antigen (CEA), alpha-fetoprotein (AFP), beta-human chorionic gonadotropin (b-HCG), and lactate dehydrogenase (LDH), is recommended, like for epithelial and non-epithelial ovarian cancers." (PMID 40842599, 2025). "If an ovarian carcinoma is suspected, serum tumor markers should be evaluated; these include CA125, carcinoembryonic antigen (CEA), alpha-fetoprotein (AFP), beta-human chorionic gonadotropin (b-HCG), and lactate dehydrogenase (LDH)." (PMID 40896427, 2025). "Examples of cancer antigens include prostate-specific antigen (PSA) for prostate cancer and cancer antigen CA-125 for ovarian cancer, carcinoembryonic antigen (CEA) for colon cancer, and alpha-fetoprotein for testicular cancer." (PMID 38739669, 2024). "Other germ cell origin biomarkers such as alpha-fetoprotein/AFP, human chorionic gonadotrophin/HCG as well as Lactate dehydrogenase/LDH are also connected to ovarian cancer." (PMID 36979610, 2023). "Protein biomarkers such as CEA, AFP, PSA, and CA-125 have been approved for detecting colorectal, liver, prostate, and ovarian cancers, respectively." (PMID 37508788, 2023).
ovarian cancer (continued). "Keywords used for the searching process were “Ovarian cancer”, “Cancer biomarkers”, “Early detection”, “Cancer diagnosis”, “CA-125”,“CA 15-3”,“CA 19-9”, “HE4”,“hCG”, “inhibin”, “AFP”, “LDH”, and others." (PMID 37629546, 2023). "As for the tumor-related proteins, like CEA, AFP, CA19-9, PSA, HCG, and CA-125 are used to detect colorectal, liver, pancreas, prostate, and ovarian cancers, respectively." (PMID 35637960, 2022). "Among the 11 serum tumor markers, AFP, CA125, CA19‐9, CA242, CEA, Ferritin, NSE and HE4 showed elevated levels and CA15‐3, HGH, and β‐HCG showed reduced levels in ovarian cancer patients." (PMID 30972954, 2019). "CA-125, CEA, AFP, LDH, CA-19-9, and beta-hCG are known to be expressed in ovarian cancer and used as tumor markers." (PMID 31351482, 2019). "In the combinations of different markers, a panel of eight markers (AFP, β‐HCG, CA125, CA15‐3, CEA, Ferritin, HGH, and NSE) showed the best performance in ovarian cancer detection (AUC = 0.873, Sensitivity = 0.727, Specificity = 0.826)." (PMID 30972954, 2019). "Furthermore, combining serum LDH with other tumor markers such as alpha-fetoprotein, CA125, and human chorionic gonadotropin can enhance the accurate determination of histological types in ovarian cancer." (PMID 39582538, 2024). "The normal concentration of AFP in saliva was 0.572 [0.530; 0.711] IU/mL, significant changes in AFP concentration were not shown both in benign ovarian pathologies (0.625 [0.541; 0.715] IU/mL) and in ovarian cancer (0.562 [0.519; 0.668] IU/mL)." (PMID 37367072, 2023). "AFP, β-HCG, cancer antigen (CA)-125, lactate dehydrogenase, carcinoembryogenic antigen and CA-19-9 levels are less specific in children than in adults for the ovarian malign tumors." (PMID 36530560, 2022). "CA125 is elevated in the serum of most women with ovarian cancer and is recommended as an ovarian cancer screening biomarker clinically in the U.S. For early detection of HCC, the most common serological test is for α-fetoprotein (AFP)." (PMID 34150633, 2021). "Herein, we investigate a high-performance microfluidic detection platform to conduct a novel panel of multiple biomarkers for the early detection of ovarian carcinoma, which include CA125, HE4, OPN, MSLN, Hsp70, CA153, AFP, IL-6, and IL-8 using a microfluidic chip." (PMID 35423342, 2021). "Testing the level of human chorionic gonadotropin (beta HCG), alpha-fetoprotein (AFP), lactate dehydrogenase (LDH), and inhibin—determined in non-epithelial ovarian cancers." (PMID 40429755, 2025).
breast carcinoma (73 papers, 2002 to 2025). "While some studies do not consider this biomarker to be sufficiently sensitive for diagnosing primary and malignant breast tumors, others have demonstrated its diagnostic value either alone or in combination with other biomarkers such as AFP, CA-153, and CEA." (PMID 40385462, 2025). "Extensive epidemiological studies have linked endogenous AFP to a reduced incidence of breast cancer." (PMID 36766292, 2023). "AFP is produced by the fetus in utero and explains, in part, why parous women have a decreased risk of breast cancer." (PMID 36766292, 2023). "Low AFP concentrations during pregnancy have been associated with increased risk of subsequent breast cancer." (PMID 22815728, 2012). "An inverse association between third trimester levels of AFP and subsequent risk of breast cancer has also been reported by an American study." (PMID 11875734, 2002). "In adulthood, two studies have recently related maternal blood levels of AFP during the second or third trimester among pregnant women to these women's subsequent risk of breast cancer." (PMID 11875734, 2002). "Both studies found that high pregnancy levels of AFP were associated with lower maternal breast cancer risk, and the authors attributed their findings to an anti-oestrogenic effect of AFP." (PMID 11875734, 2002). "Indeed, AFP has been reported to inhibit estrogen receptor (ER)-positive human MCF-7 and MTW9A rat mammary cancer growth, which is associated with the interaction between AFP and 17β-estradiol." (PMID 32019136, 2020). "It is biologically plausible that the relationship between delivery of a large infant and increased risk of breast cancer is mediated by the hormonal environment during pregnancy of high maternal concentrations of E3, low concentrations of AFP and high concentrations of PAPP-A." (PMID 22815728, 2012). "Increased levels of AFP and CA 15-3, especially at moderate and high doses, suggest a potential link to the development of breast cancer." (PMID 39659309, 2024). "Specific receptors for AFP in the membrane of human breast cancer cells were indicated as a marker of cancer cells in clinical blood samples from patients with breast carcinoma." (PMID 39057100, 2024). "Evidence for existence of a specific receptor for AFP was first demonstrated on the MCF-7 human breast cancer cell line and later on the U937 human lymphoma cell line." (PMID 37016369, 2023). "During the development of AFPep, the full-length protein was parsed to locate the anti-estrogenic and anti-breast cancer site of AFP; then, that site was manipulated to achieve a readily synthesizable, stable, orally active cyclic peptide." (PMID 36766292, 2023). "AFPep is a nine-amino acid, cyclic peptide derivative of a naturally occurring protein and is the anti-estrogenic, anti-breast-cancer active site of AFP." (PMID 36766292, 2023). "In women, high levels of a naturally occurring, anti-estrogenic protein, alpha-fetoprotein (AFP), are protective against the development of breast cancer." (PMID 36766292, 2023). "For example, cancer embryonic antigen (CEA) is used for early warning of colorectal and breast cancer, and alpha-fetoprotein (AFP) is used for early warning of stomach, colon, etc., and these traditional biomarkers are widely used in early diagnosis tumors." (PMID 35310927, 2022). "In routine physical examination and early breast cancer screening, the optimal combination of AFP + CEA + CA153 three parallel tests is recommended." (PMID 36755860, 2022). "Studies reported a protective relationship between serum alpha-fetoprotein levels and breast cancer." (PMID 35480092, 2022). "In the present analysis, Ca 15-3, FERR, and AFP showed increased levels in breast cancer patients compared with the benign breast disease controls." (PMID 34335759, 2021). "Our results showed that AFP was elevated in breast cancer patients compared with the benign breast disease controls." (PMID 34335759, 2021).